CYP24A1 (cytochrome P450 family 24 subfamily A member 1)
Diseases named in the same sentence as CYP24A1 in open-access papers (continued):
Sharing a sentence is not in itself a finding about the gene and the disease.
colorectal cancer (22 papers, 2011 to 2026). A primary or metastatic malignant neoplasm that affects the colon or rectum. "CYP24A1, encoding the mitochondrial enzyme 24-hydroxylase, plays a paradoxical role in colorectal cancer (CRC)—acting both as a physiological regulator of vitamin D metabolism and a pathological driver of tumor progression." (PMID 41228419, 2025). "Nevertheless, COX-2, CYP27B1, and CYP24A1 expressions have also been associated with the pathogenesis of human colorectal cancer linked to chronic inflammation." (PMID 38355711, 2024). "Significant inverse association was observed between cumulative methylation level of significant CpG sites in VDR (aOR, 0.28; 95% CI, 0.16–0.51) and CYP24A1 (aOR, 0.19; 95% CI, 0.09–0.40) and colorectal cancer risk." (PMID 37644572, 2023). "There were significant inverse associations between cumulative methylation levels of significant CpG sites in VDR and CYP24A1 and colorectal cancer risk." (PMID 37644572, 2023). "The cumulative methylation status at significant CpG sites of CYP24A1 was negatively associated with the risk of colorectal cancer, with an aOR of 0.19 (95% CI, 0.09–0.40; P < 0.001)." (PMID 37644572, 2023). "There is reference to the association of the CYP24A1-rs6013897 polymorphism with colorectal cancer, in addition to inflammatory reactions, however, there are few studies on cirrhosis with or without HCC, thus highlighting the contribution of the present study." (PMID 35919232, 2022). "In this study, we investigated possible mechanisms underlying the upregulation of CYP24A1 in colorectal cancer." (PMID 23463632, 2013). "Stratified analysis by sex revealed that cumulative methylation status of CYP24A1 at significant CpG sites was associated with a decreased risk of colorectal cancer in both males and females, which was consistent with the primary analysis (Pinteraction = 0.17)." (PMID 37644572, 2023). "Some studies explored CYP24A1 polymorphisms and risk for UC and colorectal cancer." (PMID 32422882, 2020). "Recently, it has been suggested that the association between colorectal cancer and reduced levels of circulating vitamin D may be related to overexpression of the vitamin D-catabolizing enzyme, CYP24A1 in the tumor." (PMID 23463632, 2013). "As a positive control, VDR binding was assessed using a proximal human CYP24A1 promoter region (-252 to -51 bp) previously confirmed as a VDR binding site by ChIP-PCR in a colorectal cancer cell line." (PMID 41505470, 2026). "In colorectal cancer, for example, hypermethylation of the CYP24A1 promoter correlates with suppressed gene and protein expression." (PMID 41228419, 2025). "This dual role—protective in physiological contexts yet deleterious in malignancy—positions CYP24A1 as both a biomarker of tumor aggressiveness and a promising therapeutic target in colorectal cancer." (PMID 41228419, 2025). "While literature suggests a link between CYP24A1 rs6013905AX and rs2762939GX SNPs and colorectal cancer (p ≤ 0.05), little is known about their relevance to IBD." (PMID 39685734, 2024). "However, the cumulative methylation level of significant CpG sites in CYP24A1 was significantly lower in colorectal cancer cases than that in controls, and it was significantly negatively associated with colorectal cancer risk, which was consistent with our hypothesis." (PMID 37644572, 2023). "In contrast, no statistical association was found between the methylation status of VDR, CYP24A1, and CYP27B1 at all CpG sites and the risk of colorectal cancer." (PMID 37644572, 2023). "The cumulative methylation levels of significant CpG sites in VDR and CYP24A1 and all CpG sites in CYP2R1 were inversely associated with colorectal cancer risk." (PMID 37644572, 2023). "This study indicated that the cumulative methylation levels of significant CpG sites in VDR and CYP24A1 and all CpG sites in CYP2R1 were inversely associated with colorectal cancer risk." (PMID 37644572, 2023).
colorectal cancer (continued). "The cumulative methylation levels of the VDR and CYP24A1 were significantly lower in colorectal cancer cases than those in controls (P < 0.05)." (PMID 37644572, 2023). "In this context, we conducted this study to examine the association between methylation levels of four vitamin D metabolic pathway-related genes (VDR, CYP24A1, CYP27B1 and CYP2R1) from blood and the risk of colorectal cancer." (PMID 37644572, 2023). "In Model 2, the value of cumulative methylation of VDR and CYP24A1 at significant CpG sites in the diagnosis of colorectal cancer was evaluated." (PMID 37644572, 2023). "In nasopharyngeal carcinoma, miR-1278 exerts tumor-suppressive effects by targeting ATG28; miR-1278 expression is downregulated in colorectal carcinoma and tumor cell metastasis is inhibited by the targeting of CYP24A1, BTG2, and other downstream target genes." (PMID 38025524, 2023). "In conclusion, here we provide evidence that the overexpression of CYP24A1 in a mouse xenograft model of colorectal cancer results in more aggressive tumours." (PMID 26238339, 2016). "The DNA methylation of CYP24A1 can regulate its gene expression and may play a role in the occurrence and progression of colorectal cancer (CRC)." (PMID 39858498, 2025). "Consistent with our results, a study from Austria including 20 colorectal cancer cases reported that the methylation levels of the two regions of the CYP24A1 promoter in cancer tissues were lower than that in normal mucosa, but the difference was not statistically significant." (PMID 37644572, 2023). "In our study, colorectal cancer cases had lower cumulative methylation level of significant sites in CYP24A1, suggesting that CYP24A1 hypomethylation may contribute to the development of colorectal cancer by regulating high expression of 24-hydroxylase." (PMID 37644572, 2023). "Therefore, CpG site 53 in the CYP24A1 gene was excluded that was more frequently methylated in colorectal cancer cases than in controls." (PMID 37644572, 2023). "Similar studies also explored CYP24A1 polymorphisms for colorectal cancer risk, but risks for colitis were not discussed." (PMID 32422882, 2020). "We hypothesized that the methylation level of CYP24A1 could be negatively associated with colorectal cancer risk, while the methylation levels of VDR, CYP2R1 and CYP27B1 could be positively associated with colorectal cancer risk." (PMID 37644572, 2023). "Moreover, a recent study showed that the upregulation of CYP24A1 and PFDN4 as well as nearby lncRNAs may be used as the potential diagnostic biomarker in colorectal cancer." (PMID 34422647, 2021). "This might be a further explanation for how a WD promotes colorectal tumorigenesis, as CYP24A1 expression is known to be increased in colorectal tumors, and we have shown previously that overexpression of CYP24A1 increased aggressiveness of human colorectal cancer cells in a xenograft model." (PMID 31877961, 2019). "Below, we highlight the role of CYP24A1 in selected intestinal disorders, including IBD, celiac disease, and colorectal cancer." (PMID 41228419, 2025). "In colorectal cancer, knockdown of SQLE reduced calcitriol, the active metabolite of VitD3, leading to a reduction in cytochrome P450 family 24 subfamily A member 1 (CYP24A1) levels, which suppressed the phosphorylation and activation of ERK." (PMID 36091156, 2022). "In colorectal cancer (CRC) the vitamin D catabolizing enzyme 1,25-dihydroxyvitamin D 24-hydroxylase (CYP24A1) is overexpressed with a potentially significant, positive impact on the catabolism of 1,25-dihydroxyvitamin D3 (1,25-D3)." (PMID 23463632, 2013). "The current findings indicate that the DNA methylation state of the CYP24A1 promoter does not play a role in the pathogenesis of colorectal cancer." (PMID 23463632, 2013).
idiopathic infantile hypercalcemia (18 papers, 2013 to 2025). "CYP24A1 loss-of-function mutations cause infantile hypercalcemia (IIH) and represent a genetic risk factor for serious adverse effects in response to vitamin D supplementation." (PMID 35238975, 2023). "Infantile hypercalcemia type 1 (HCINF1), previously known as idiopathic infantile hypercalcemia, is caused by mutations in the 25-hydroxyvitamin D 24-hydroxylase gene, CYP24A1." (PMID 35956396, 2022). "Infantile hypercalcemia is an autosomal recessive disorder caused either by mutations in the CYP24A1 gene (20q13.2) or in the SLC34A1 gene (5q35.3)." (PMID 33952337, 2021). "In 2011 new research found that Idiopathic infantile hypercalcemia (IIH) was associated with mutations in the CYP24A1 gene involved in vitamin-D metabolism." (PMID 28874334, 2018). "Major alterations in the enzymatic activity of CYP24A1 can be due to mutations of the CYP24A1 gene located on chromosome 20p13 (20.5 kb, 12 exons) that cause idiopathic infantile hypercalcemia." (PMID 28425954, 2017). "These mutations cause rare hereditary metabolic bone conditions, like hereditary vitamin D-resistant rickets (VDR), vitamin-D-dependent rickets type 1A (CYP27B1), type 1B (CYP2R1) or idiopathic infantile hypercalcemia (CYP24A1)." (PMID 35238975, 2023). "These patients presented with phenotypic and laboratory characteristics that were originally reported as idiopathic infantile hypercalcemia (IIH), since the first described cohort of patients with CYP24A1 mutations in the 1950s." (PMID 34858904, 2021). "Unlike inactivation mutation in CYP24A1 (MIM 126065) which causes infantile hypercalcemia-1 (HCINF1), patients with HCINF2 respond rapidly to phosphate supplementation." (PMID 29505567, 2018).
chronic kidney disease (15 papers, 2021 to 2026). Impairment of the renal function secondary to chronic kidney damage persisting for three or more months. "Two patients developed grade 2 chronic kidney disease at the end of the follow-up, both of them had mutations in CYP24A1." (PMID 34858904, 2021). "In chronic kidney disease, expression of Cyp24a1 is increased possibly accounting for decreased 1,25(OH)2D3 due to degradation." (PMID 39043847, 2024). "Here, we describe the responses of mice with inducible global deletion, kidney-specific, and intestine-specific deletion of Cyp24a1 to dietary calcium challenge and chronic kidney disease (CKD)." (PMID 39688907, 2024). "In a recent long-term follow-up of 18 patients with CYP24A1 and SLC34A1 mutations, impaired kidney function at a mean age of 23.8 years was found in 77%, including two adults with end-stage renal disease." (PMID 34858904, 2021). "Furthermore, chronic conditions such as chronic kidney disease (CKD), often influenced by environmental stressors, are associated with altered CYP24A1 activity in both systemic and intestinal compartments." (PMID 41228419, 2025). "The overexpression of CYP24A1 has been revealed to be involved in developing chronic kidney diseases and might be responsible for decreasing vitamin D active forms in circulation." (PMID 37528997, 2023). "An abnormal status of the upregulation of CYP24A1 occurs in many diseases, including chronic kidney disease (CKD)." (PMID 35883516, 2022).
asthma (14 papers, 2005 to 2025). "The presence of certain SNPs in CYP24A1 have also been associated with atopic diseases such as AD and asthma." (PMID 37632926, 2023). "In the SLSJ population, three SNPs in the CYP24A1 gene showed modest evidence of association with asthma or atopy (p < 0.05)." (PMID 19852851, 2009). "In the replicate samples, SNPs in the IL10 and CYP24A1 genes were again modestly associated with asthma and atopy (p < 0.05)." (PMID 19852851, 2009). "Four out of the eight genotyped SNPs in the CYP24A1 gene were also modestly associated with asthma or atopy (range of p values = 0.051 to 0.015)." (PMID 19852851, 2009). "Similar to the SLSJ study, some SNPs in the IL10 and CYP24A1 genes were modestly associated with asthma or atopy." (PMID 19852851, 2009). "Haplotype association were found only for CYP24A1, the main calcidiol degrading enzyme, where a frequent 5-point-haplotype was associated with asthma (p = 0,00063), total IgE (p = 0,0014), calcidiol (p = 0,0043) and calcitriol (p = 0,0046)." (PMID 16600026, 2006). "RXR has already been tagged by a SNP in a previous study and also 3 SNPs in CYP24A1 (rs751089, rs2296241 and rs2248137) were significantly associated with asthma (unpublished own observation)." (PMID 15651992, 2005). "Both genetic variants in VDR and CYP24A1 have been associated with risk of asthma and atopy." (PMID 41149648, 2025). "SNPs in the vitamin D pathway (CYP27A1, CYP27B1, CYP2R1, CYP24A1, and GC) affecting 25OHD levels demonstrated moderate effects on risk of asthma in a prior adult study, but the role of these variants on asthma risk later in life is unknown." (PMID 28486474, 2017). "Additionally, our literature review found evidence of an association in children between CYP24A1 mRNA and LL-37, an immunomodulating peptide potentially related to asthma." (PMID 28486474, 2017). "The addition of 1,25D3 to polyI:C-stimulated BSMCs significantly induced CYP24A1 mRNA expression in asthma (5547 ± 454-fold increase, p < 0.001) and COPD (3565 ± 311-fold increase, p < 0.01) as compared to control groups." (PMID 34512638, 2021). "Further investigation revealed several lipid-associated enzymes implicated in asthma pathogenesis to be encompassed by asthma-SEs (e.g., PTGS1, PTGS2, CYP24A1)." (PMID 33362848, 2020). "SNPs located in five genes, including IL10, CYP24A1, IL1RL1, CYP2R1 and CD86, showed modest association with asthma or atopy in an asthma family study derived from the Saguenay_Lac-Saint-Jean population." (PMID 19852851, 2009). "A number of SNPs in the IL10, CYP24A1, CYP2R1, IL1RL1 and CD86 genes were modestly associated with asthma and atopy (p < 0.05)." (PMID 19852851, 2009). "The CYP24A1 rs6068816 and rs4809957 polymorphisms have not been related in our study to the risk of developing asthma." (PMID 36839181, 2023). "Therefore, we performed sensitivity analyses excluding the CYP2R1 and CYP24A1 SNPs (rs10741657 and rs6013897, respectively) from our MR instruments in our asthma analysis and excluding the CYP2R1 SNP (rs10741657) in our atopic dermatitis and IgE analysis." (PMID 28486474, 2017). "In addition, the only CYP24A1 SNP (rs2248359) genotyped in common between the German and SLSJ population showed a consistent result with an increase risk of asthma associated with the C allele." (PMID 19852851, 2009). "Again modest associations were observed for the IL10, CYP24A1 and CD86 genes for asthma or atopy." (PMID 19852851, 2009). "Variants in CYP2R1, CYP27B1 and CYP24A1 or other genes in the metabolic pathway of vitamin D have not been tested so far with asthma or allergy but several of the VDR-controlled genes tested here already have been associated with asthma and allergy." (PMID 16600026, 2006). "To assess the effect of the independent vitamin D pathways on risk of asthma, we analyzed SNPs near genes implicated in 25OHD synthesis (DHCR7 and CYP2R1) and metabolism (GC and CYP24A1) separately and found that none were associated with increased risk of asthma." (PMID 28486474, 2017).
asthma (continued). "At least one positive SNP with a TDT of p < 0.05 for asthma or total IgE and calcidiol or calcitriol was seen in IL10, GC, IL12B, CYP2R1, IL4R, and CYP24A1." (PMID 16600026, 2006). "SNPs in 5 genes showed a p-value < 0.05 with asthma (IL10, IL12B, VDR, CARD15 and CYP24A1)." (PMID 16600026, 2006).
diabetes (10 papers, 2012 to 2025). "We observed high levels of renal Cyp24a1-splicing variant mRNA expression in streptozotocin-induced diabetes rats." (PMID 32001956, 2020). "Here, we investigated the association between Cyp24a1, a vitamin D catabolic enzyme, and abnormalities in vitamin D metabolism in streptozotocin-induced diabetes rats, an animal model of type 1 diabetes." (PMID 32001956, 2020). "As such, there is an incomplete understanding of the association between Cyp24a1 expression and the low vitamin D levels in diabetes, and levels of 1,25(OH)2D3 in rats having STZ-induced type 1 diabetes have not been measured before." (PMID 32001956, 2020). "On the other hand, similar to an earlier short-term study in rat, we observed that 4 weeks of STZ-induced diabetes increases the expression of the vitamin D catabolic enzyme Cyp24a1 in the kidney." (PMID 35524739, 2022). "Furthermore, it has been suggested that a targeted CYP24A1 inhibition approach could be of therapeutic usefulness for other conditions associated with CYP24A1 dysregulation, such as some malignancies, psoriasis, and diabetes." (PMID 35883516, 2022). "Plasma 1,25-dihydroxyvitamin D [1,25(OH)2D] levels were significantly lower in streptozotocin-induced diabetes rats and renal Cyp24a1 mRNA expression levels were increased." (PMID 32001956, 2020). "Diabetes conditions clearly destabilize vitamin D metabolism, and our study suggests that increased CYP24A1 activity is a major contributor to this effect." (PMID 23119081, 2012). "Our data suggest that control of CYP24A1 increase during diabetes has a beneficial effect on senescence induction and caspase-3 increased expression." (PMID 23119081, 2012). "We also studied whether STZ-induced diabetes affects Cyp24a1, the major vitamin D catabolic enzyme in the kidney." (PMID 35524739, 2022). "High plasma corticosterone levels in diabetes may affect transcriptional regulation to promote increases in Cyp24a1 expression." (PMID 32001956, 2020). "Our results suggest that high plasma corticosterone levels in diabetes may be one factor that induces transcriptional up-regulation of Cyp24a1 gene." (PMID 32001956, 2020). "Taken together, our results indicated that high Cyp24a1 expression levels may play a role in the decrease of plasma 1,25(OH)2D levels in streptozotocin-induced diabetes rats." (PMID 32001956, 2020). "We concluded that diabetes induces an increase in CYP24A1 expression, destabilizing vitamin D metabolism in the renal proximal tubules, leading to cellular instability and apoptosis, and thereby accelerating tubular injury progression during diabetic nephropathy." (PMID 23119081, 2012). "The effects on risk of diabetes were assessed by a genetic score using two 25(OH)D synthesis SNPs (DHCR7-rs12785878 and CYP2R1-rs10741657), with and without the addition of SNPs affecting the transport (GC/DBP-rs2282679) and catabolism (CYP24A1-rs6013897) of 25(OH)D." (PMID 29718904, 2018). "In this study, we investigated the relationship between change in Cyp24a1 expression change and abnormalities in vitamin D metabolism in rats with STZ-induced diabetes." (PMID 32001956, 2020). "In conclusion, our study indicated that alterations in renal Cyp24a1 expression rather than renal Cyp27b1 expression may be the primary cause to decrease in plasma 1,25(OH)2D levels in rats with STZ-induced diabetes." (PMID 32001956, 2020).